CD4 (CD4 molecule)
Diseases named in the same sentence as CD4 in open-access papers (continued):
Sharing a sentence is not in itself a finding about the gene and the disease.
infection (continued). "Among α-PD-L1 treated mice, neither CD4+ depletion throughout infection nor CD4+ depletion later in infection had any significant effect on the development of ECM." (PMID 22319445, 2012). "Here, we employed a latency model that achieves high levels of infection without requiring stimulation to identify a population of latently infected resting CD4+T cells that express Gag but do not support viral spread." (PMID 22911005, 2012). "Moreover, we have seen that the parasite at early stages of the infection in vaccinated animals boosted both CD8+ and CD4+ T cells." (PMID 22715418, 2012). "All viral pseudotypes were functional, leading to infection of NP2/CD4/CCR5 cells at least 100-fold above Env-negative particles." (PMID 22693444, 2012). "CD4 T-cells with a Th2 phenotype have been proposed to overall suppress inflammation and demyelination: IL-4 treatment during the early chronic phase of TMEV infection resulted in a more benign disease phenotype, with reduced anti-TMEV antibody responses." (PMID 22348089, 2012). "In the memory compartment, latent MCMV-infection also led to a slight expansion of blood CD4+ Tem but not of Tcm in young mice and this difference was partially maintained for Tem during ageing." (PMID 22916013, 2012). "The influence of early neutrophil depletion on CD4 priming was no longer apparent when OT-II cells were transferred 14 days post-infection with Lm SP-OVA, at a time when infected DCs no longer harbored neutrophil markers." (PMID 22359507, 2012). "Although T-bet and CD127 expression were not directly addressed, Foxp3− ‘effector’ CD4+ T cells also appear to be the major CD4+ T cell subset producing IL-10 during infection of mice with L. major." (PMID 22911108, 2012). "The capacity of VF to mediate tethering and co-ordination of neighboring CD4 T cell contacts supports their role as viral synapse (VS) precursors, with VS formation triggered by HIV envelope and eventually mediating CD4 T cell infection." (PMID 22685410, 2012). "CD4+ T cells were isolated and stimulated with IL-2/PHA, prior to infection with isogenic viruses." (PMID 22537596, 2012). "The rapid turnover of SIV DNA in animals with high viral load suggests the resting pool of CD4+ T cells and the pool of SIV DNA may be much more dynamic than previously thought during active infection." (PMID 22496643, 2012). "Based on these data, SAMHD1 is necessary and sufficient to inhibit infection of myeloid cells and quiescent CD4+ T cells by lentiviruses not expressing Vpx." (PMID 23344558, 2012). "This is consistent with studies reporting immunological alterations related to HIV persistence in CD4+ T-cells and chronic immune activation in SP subjects, especially after many years of infection in the absence of ART." (PMID 22470433, 2012). "In addition to being infected, there is also evidence that macrophages archive HIV-1 virions for transfer to CD4+ T lymphocytes via the virological synapse, an HIV-induced interface between two cells that facilitates cell to cell infection." (PMID 23344558, 2012). "LAINefdd infection did not result in depletion of CD4+ T cells in lymph node (LN), spleen, bone marrow (BM), lung and liver reflecting what was observed in peripheral blood." (PMID 22640559, 2012). "The majority of HIV controllers are also defined by the absence of massive CD4+ T-cell depletion, even after 10 years of infection." (PMID 23243424, 2012). "No Th2 or Th17 CD4 T cell response was detected at either of these time points after intravenous infection (data not shown)." (PMID 22275869, 2012). "Additional studies in the SIV/macaque model revealed that up to 60% of memory CD4+CCR5+ T cells may be selectively infected and lost during this early stage of infection." (PMID 22319447, 2012). "Overall, the effects of MCMV-infection on the CD4-compartment were much more subtle but similar to CD8 as an overall trend, whereas Tx had a more profound and immediate impact on the total and the naïve CD4 compartment." (PMID 22916013, 2012).
infection (continued). "To do this, we cultured untreated resting CD4+T cells or prestimulated the cells for 3 days with IL-7, CCL19, or CD3/28 beads and then spinoculated the cells with HIV, after which we measured the ratio of integrated to total HIV DNA 48 hours post infection." (PMID 22911005, 2012). "While CD8+ T cells, CD4+ T cells and B1 B cells cooperate to clear a primary IAV infection from the airway, activation of T-dependent B cell responses is central in developing long-term protection from re-infection." (PMID 22792401, 2012). "The in trans phenotype is defined as the binding/uptake of virus from the surrounding inoculum, which can be then transferred from DC to CD4 -T cells in the short-term (effectively between 4 to 6 hours) independent of DC infection." (PMID 22685410, 2012). "In contrast all six macaques infected with the Vpx mutant SIVs showed no reduction in CD4 counts at 10 days post infection (CD4 increased by 3.1-79%, mean 31%, t < 0.03 compared to wild-type animals)." (PMID 22531456, 2012). "The susceptibility of BALB/cAnNCr mice is thought to be directly caused by a defective/absent CD4+ T-cell subset, providing another example how CD4+ T-cells may regulate the overall phenotype observed in this model, acting in the earliest, most acute stage immediately after infection." (PMID 22348089, 2012). "The CD4-dependent HIV particles may be degraded by endosome proteases in acidic endosomes, and the infection titer is reduced." (PMID 23304142, 2012). "In the present study, we demonstrate that SAV-3 infections induce mRNA transcripts of genes including IFN-α and its stimulated genes (ISG) at early time, followed by IFN-γ, TNF-α, IL-12, IL-10, IL-8, CD3ε, CD4, CD8, TCR-α, MHC-I, and MHC-II as the infection progresses." (PMID 23116479, 2012). "Indeed, in stark contrast to what has been observed during acute LCMV infection, we show that OX40 shapes both the CD4 and CD8 T cell response during persistent LCMV cl13 infection including T cell dependent antibody responses." (PMID 22969431, 2012). "In the spleen, CD4+ and CD8+ cells vary in their contribution toward production of IFN-γ over the course of infection with CD8+IFN-γ+ cells persisting at later time points after infection." (PMID 22428026, 2012). "Indeed, several studies using naturally infected animals showed a correlation between increased numbers of CD4+ and CD8+ T-cells with resistance against infection by L. infantum." (PMID 23189161, 2012). "Similarly, infection with Salmonella (BRD509) allowed detection of an expanded population of flagellin- and SseJ-specific CD4 T cells." (PMID 22275869, 2012). "Since Salmonella grow intracellularly in vivo, a protective role for Salmonella-specific Th17 CD4 T cells during primary infection is not immediately obvious." (PMID 22275869, 2012). "The natural log of CD4 (lnCD4) was the dependent variable in all models; this measure declines linearly and is assumed to be independent of time of infection." (PMID 23185441, 2012). "Increased numbers of CD4+ and CD8+ naïve (CD4+CD44lowCD62Lhigh and CD8+CD44lowCD62Lhigh, respectively) as well as CD4+ and CD8+ effector (CD4+CD44highCD62Llow and CD8+CD44highCD62Llow) T cells were detected at week 2 after infection." (PMID 23226464, 2012). "In agreement with the observation of reduced OX40 receptor expression during acute infection, the percentage of OX40−/− CD4 and CD8 TCRtg cells within the ‘transferred cells’ gate was significantly lower in cl13 infected animals than in Armstrong infected animals." (PMID 22969431, 2012). "Primary CD4+ T cells were activated with CD3 and CD28 mAbs for 24 hours before infection with HIV." (PMID 21698207, 2011). "In order to assess the scope of such systemic changes we analyzed the gene expression changes that occurs post infection in both the targeted (i.e. CD4+ central memory) and non-targeted (Naïve CD4+ and CD8+) subsets and compared to the pre-infection status." (PMID 22043290, 2011).
infection (continued). "Nucleoside reverse transcriptase inhibitors (NRTIs) are more effective in macrophages than in CD4+ T-cells for early viral inhibition; non-NRTIs are equally effective in macrophages and in CD4+ T-cells for early infection." (PMID 21489275, 2011). "Collectively, these data demonstrate a lack of CD4+ T cell involvement and a novel role for IL-13 in innate responses to infection." (PMID 21573182, 2011). "In one study using the intraperitoneal infection route one of twelve cell lines was CD4- CD8α+ but this lacked expression of CD8β." (PMID 21573129, 2011). "However, the absolute numbers of CD4+ and CD3+ T cells were significantly lower in those born during the hungry/high infection compared to the harvest/low infection season." (PMID 21676219, 2011). "Despite the potentially advantageous broadening of tropism associated with a lower dependence on CD4 for infection, HIV-1 strains that are fully independent of CD4 have been identified only rarely in infected people." (PMID 21731494, 2011). "In contrast, Env-, Tat-, and Nef-specific CD8+ T cell clones failed to recognize SIV-infected CD4+ T cells before twelve hours post-infection when SIV begins to downregulate surface CD4 and MHC class I molecules." (PMID 21887264, 2011). "Suppression of endosome acidification or endocytosis by inhibitors or by an Eps15 dominant negative mutant reduced the infectivity of mNDK in which CD4-dependent infections were not significantly impaired." (PMID 21541353, 2011). "Dynasore treatment more efficiently attenuated the CD4-independent mNDK vector infection than the CD4-dependent mNDK or HXB2 (data not shown) vector infection in all examined cells (P<0.05)." (PMID 21541353, 2011). "Cystatin C expression did not affect the mNDK vector infection in CD4-negative and –positive 293T cells." (PMID 21541353, 2011). "Nef enhances virion infectivity in single round infection assays, even when the virus is produced in CD4-negative cells." (PMID 21819585, 2011). "In contrast, slow/low, NSI, M-Tropic viruses, isolated initially from asymptomatic patients with no sign of CD4 decline shortly after infection, were thought to be less cytopathic." (PMID 21284905, 2011). "Depletion of CD4+ cells in cattle during infection further reduces circulating type I IFN, but infection is still resolved, indicating that the presence of type 1 IFN in the circulation may not have any bearing on the resolution of disease." (PMID 22014145, 2011). "We concluded that both non-conventional and conventional CD4+ T cells promptly respond to P. chabaudi malaria, but the majority of splenic CD4+ T cells activated during the first days of infection are restricted by class II MHC molecules." (PMID 21814579, 2011). "In addition, 3-HK mice showed, at the chronic phase of the infection, an increased CD8+/CD4+ cell ratio and a population of T. cruzi-specific cells capable of secreting Th1-type cytokines." (PMID 22028903, 2011). "DC-SIGN has been implicated in both productive infection of DCs and the DC-mediated trans infection of CD4+ T cells that occurs in the absence of replication." (PMID 22163292, 2011). "Cystatin C did not affect the cell surface expression of CXCR4 in HeLa cells, indicating that cystatin C does not increase the CD4-independent vector infection by enhancing CXCR4 expression." (PMID 21541353, 2011). "Not all mannose-binding C-type lectin receptors enhance infection either in trans or when expressed in cis with CD4 and co-receptor." (PMID 22163292, 2011). "Our studies examining IL-17A expression within lung leukocytes during C. neoformans strain H99γ infection suggest that neutrophils are the predominant source of IL-17A, rather than CD4+ T cells, which has been shown in other systems." (PMID 21359196, 2011).
infection (continued). "At 6 d post-infection in broilers, an E. acervulina or E. maxima infection induced a CD8+ T-cell and macrophage response in their respective intestinal sites, whereas E. tenella induced a cecal CD4+ T-cell and macrophage response." (PMID 21297942, 2011). "Such superantigens do not account for the expansion of 2W:I-Ab-specific CD4+ T cells following GAS-2W infection, despite the fact that some of these T cells express the relevant TCR V beta chains." (PMID 21966268, 2011). "However when the freshly isolated DCs were infected with various HIV-1 strains in vivo, they were permissive for productive infection with the macrophage tropic HIV-1 (R5 HIV-1) and the infected DCs transferred HIV-1 to CD4 T cells." (PMID 21994776, 2011). "A synthetic cathepsin B inhibitor, CA-074Me, also enhanced the CD4-independent mNDK vector infection in HeLa cells, but did not affect the CD4-dependent infection." (PMID 21541353, 2011). "IL-4 producing CD4+ T cells were present at the site of infection, indicating that differentiation and migration to site of infection were not a problem." (PMID 21747996, 2011). "It is surprising then that IL-15 KO mice do not succumb more rapidly to long-term infection with T. gondii, given that CD4 T-cell help has been shown to be required for long-term CD8 T-cell memory responses to LCMV and Listeria monocytogenes." (PMID 21687650, 2011). "The BFLA-1 treatment of TE671 cells expressing human CD4 did not affect infection by an HIV-1 vector carrying the Env protein of the CXCR4-tropic HXB2 HIV-1 strain." (PMID 22022555, 2011). "The CD4+ T cells also play other roles in the defense against infection that is independent of IFN-γ production." (PMID 21234341, 2011). "Although CD4+ T cells play crucial role in prophylactic action against M. tb., however CD8+ T cells are also equally needed for the same, especially during the chronic phase of infection." (PMID 21853054, 2011). "The fact that animals are easily infected, support high peak viral replication, and initially lose intestinal CD4+ T cells demonstrate these animals are not inherently resistant to infection, and have ample viral target cells to support replication." (PMID 21464951, 2011). "Previous studies have shown that depletion of CD8+ but not CD4+ T cells 6 days post-infection, just prior to the onset of neurological signs, prevents the development of ECM." (PMID 21494565, 2011). "The CD4-TLR4 transfection did not affect the CD4-dependent HIV-1 vector infection in 293T/CD4 cells." (PMID 21541353, 2011). "Expression of the main receptor for RANTES, CCR5, is also upregulated on LCMV-specific CD4 and CD8 T cells during both acute and chronic LCMV infection suggesting that not only do T cells produce RANTES upon infection but they also have an increased ability to bind RANTES." (PMID 21814510, 2011). "Treatments with these inhibitors did not reduce the cell surface expression of CXCR4, indicating that abrogation of the CD4-independent infection by the endosome acidification inhibitors is not due to the suppression of CXCR4 expression." (PMID 21541353, 2011). "DCs and LCs bind HIV and transfer virus to permissive CD4+ T cells in a process termed trans infection that does not require HIV replication in DCs or LCs." (PMID 22163292, 2011). "These resultsindicate that during M. tuberculosis infection,CD4+ effector T cells are not stimulated at their maximumpotential frequency at the site of infection in the lungs." (PMID 21637811, 2011). "DC could capture MV from the respiratory tract using dendrites protruding through the epithelium and transmit virus to CD4+ and CD8+ T-lymphocytes, leading to infection." (PMID 21304593, 2011). "Finally, following infection with NL4.3Δnef/EGFP of CCL19-treated and IL-2-PHA activated CD4+ T-cells, EGFP expression was 0% and 2% respectively (n = 1)." (PMID 21992606, 2011).
infection (continued). "In contrast, in transformed and resting CD4 T cells microtubule integrity was not required for infection, indicating that short cytoplasmic distances in T cells can be overcome by actin-dependent transport." (PMID 21994805, 2011). "This is consistent with the overall outcome of the VAX003 trial where immunization with AIDSVAX B/E did not significantly affect the rate of infection, the VL, the CD4+ count, or the clinical outcome of vaccine recipients compared to placebo recipients." (PMID 21423744, 2011). "Correlation analysis revealed that while in WT infection CD8 immune activation correlates with CD4 decline this was not true for V38E infection." (PMID 21255440, 2011). "Our long-term goal is to engineer HIV-resistant CD4+ T cells in infected individuals that can be reinfused and hopefully enable them to control infection in the absence of anti-viral drugs." (PMID 21533216, 2011). "Interestingly, we observed an increase in the proportion of CD69+ cells in the BAL as early as 24 hours post-infection, and nearly 60% of BAL CD4+ T cells were CD69+ at 48 hours." (PMID 21647373, 2011). "Viral load at six months, however, did not correlate with progression; likewise, neither did CD4 cell count at baseline or six months, which underscores the need to identify other markers of progression at this early stage of infection." (PMID 21831310, 2011). "We next sought to investigate the differences in the CD4+ and CD8+ T cells in the lungs and spleens of mice infected with the epidemic strain M. massiliense CRM-0019 compared to reference strain CIP 108297 after 30 and 60 days of infection." (PMID 21931831, 2011). "CD4/CXCR4 clustering was dependent on actin polymerization and is required for entry and infection." (PMID 21994805, 2011). "The inhibitory activity of all siRNAs was previously tested in U87.CD4.CXCR4 cells with replication competent, primary isolate virus v120-A or v126-D by detecting HIV-1 reverse transcriptase activity at different time points post-infection." (PMID 21232148, 2011). "However, detection of CD4+ and CD8+ T cell responses during acute phase of infection is an important prediction of outcome of infection." (PMID 21477382, 2011). "Even when the SG tissue was heavily infected by MCMV two and four weeks post infection, frequencies of CD11c+, MHCII+, CD8α+, DEC205+, B220−, CD4− cells among the overall SG-resident APC population remained very low (<1.5%) and total numbers remained far below their splenic counterparts." (PMID 21901102, 2011). "To verify the participation of CD4+CD25+ cells in the regulation of autoimmune responses during EAE, we transferred purified CD4+CD25+ T cells from P. chabaudi-infected mice four days after infection into MOG35-55-immunized mice." (PMID 21464982, 2011). "Since the prevalence of culture-proven active infection and TB disease rises steeply with falling CD4 cell counts, the negative predictive value of screening algorithms is significantly diminished in patient groups with low CD4 cell counts." (PMID 20936108, 2011). "But when 293T cells were treated with CA-074Me at a lower concentration, cathepsin B activity in the treated 293T cells was not affected and the CD4-independent infection was not enhanced." (PMID 21541353, 2011). "LCMV-cl13 infection of CD4-/- mice is never brought under control and, although an initial effector-like response is mounted, severe CD8 T cell exhaustion develops as the chronic infection persists." (PMID 21980291, 2011). "Since most of the mucosal CD4+ T-cells are activated memory cells expressing the viral coreceptor CCR5, viral replication leads to a massive and almost complete depletion of CD4+ T-cells in all stages of infection." (PMID 21481223, 2011). "Because the extracellular domain of CD4-TLR4 was derived from mouse CD4, it should not directly affect the CD4-independent HIV-1 vector infection." (PMID 21541353, 2011).